RUNX2 (RUNX family transcription factor 2)
Diseases named in the same sentence as RUNX2 in open-access papers (continued):
Sharing a sentence is not in itself a finding about the gene and the disease.
lymphoma (17 papers, 2010 to 2025). A malignant (clonal) proliferation of B- lymphocytes or T- lymphocytes which involves the lymph nodes, bone marrow and/or extranodal sites. "In Marek’s disease (MD), circRUNX2.2 promoted lymphoma cell proliferation via RUNX2 activation, indicating an oncogenic role, and genome-wide profiling revealed both host- and virus-derived circRNAs." (PMID 41321575, 2025). "It appears that the result of Ccr7/9 activation in Runx2/MYC lymphomas is likely to be paracrine growth stimulation, as expression of the cognate ligands (Ccl19, 21, 25) is restricted to thymic stromal cells." (PMID 24586197, 2014). "MYC and Runx2 transgenes each cooperate with MoMLV to accelerate lymphoma onset to around 60 days post-infection." (PMID 24586197, 2014). "Moreover, declining levels of ligand transcripts in Runx2/MYC thymus offers a rationale for the accelerated dissemination of lymphoma cells towards highly expressing peripheral lymphoid tissues." (PMID 24586197, 2014). "Similarly, in lymphoma, overexpression of RUNX2 and MYC results in the "collaboration" of the two corresponding proteins to attenuate apoptosis and promote proliferation." (PMID 20465837, 2010). "In Marek’s disease (MD), circRUNX2.2 (gga_circ_0009437) promotes lymphoma-cell proliferation by enhancing its parental gene in cis and recruiting CHD9 at the RUNX2 promoter, consistent with a ceRNA-coupled transcriptional mechanism." (PMID 41321575, 2025). "It is also worth to note that no obvious evidence of lymphoma was detected by the analysis of our mice, given that there was no severe trabecular and cortical bone loss, no decreased osteoclast number, serum TRAcP 5b concentration or no downregulation of Runx2 and Bglap detected." (PMID 36967771, 2023). "Notably, ChIP-seq data of lymphoid cancers, including BCP-ALL, showed that RUNX2, ERG, and ETS1 bind to over 70% of the selected 108 loci." (PMID 38926853, 2024). "Falling expression of ligand genes in 10-day Runx2/MYC thymus may be due to down-regulation or simple occlusion of non-lymphoid cells by nascent lymphoma cells, which is virtually complete at later stages." (PMID 24586197, 2014).
glioma (16 papers, 2010 to 2025). A benign or malignant brain and spinal cord tumor that arises from glial cells (astrocytes, oligodendrocytes, ependymal cells). "Collectively, our study identifies GSK3 as a switch that determines the balance between oncogenic and migratory programs, and highlights its downstream effector RUNX2 as a transcription factor newly linked to poor prognosis in low-grade glioma." (PMID 40307935, 2025). "Our results highlight the specific relationship between the IDH mutation in low-grade glioma, GSK3 expression, and RUNX2 target gene expression." (PMID 40307935, 2025). "Immunohistochemistry of RUNX2 has revealed expression in rat cortical astrocytes as well as in a glioma cell line." (PMID 31083672, 2019). "A low miR-152 expression enhanced cell proliferation, whereas a high miR-152 expression promoted glioma cell apoptosis by regulating the expression of Runt Related Transcription Factor 2 (Runx2)." (PMID 30583549, 2018). "Studies of the relationship between Runx2 and Galectin-3 demonstrated that Runx2 mediated the expression of Galectin-3 in skeletal tissue, human glioma cells, and human pituitary tumor." (PMID 28264434, 2017). "Knockdown of Runx2 was shown to be accompanied by a reduction in both galectin‐3 mRNA and protein levels by at least 50%, dependent on the glial tumor cell line tested." (PMID 19371355, 2010). "Runx2 is a member of the Runx family of transcription factors expressed in a variety of human glioma cells, whose expression pattern in these cells strongly correlates with that of galectin‐3, but not with that of other galectins." (PMID 19371355, 2010). "The regulation of galectin‐3 expression by Runx‐2 has been recently suggested to contribute to the malignant progression of glial tumor." (PMID 19371355, 2010). "Furthermore, increased RUNX2 expression in IDHmut glioma patients correlated with significantly impaired survival, which has not been observed in glioblastoma patients." (PMID 40307935, 2025). "Our experiments identify RUNX2 as a transcription factor downstream of GSK3 activity that mediates a pro-proliferative cell state and whose increased expression is associated with impaired survival in IDHmut glioma patients." (PMID 40307935, 2025). "In addition, RUNX2 promotes malignant progression in glioma and maintains MS tissue homeostasis through IGF signalling." (PMID 37357610, 2023). "A recent study showed that miR-152 could regulate glioma cell proliferation and apoptosis by targeting Runx2." (PMID 32717724, 2020). "Furthermore, RUNX2 is typically expressed at higher levels in IDHwt compared to IDHmut gliomas." (PMID 40307935, 2025). "We detected genes upregulated in PBT030 cells, such as SOX2, MYCN, NOS2, RUNX2, and VEGFA, while PBT147 cells upregulated level of PTEN, STAT6, CA9 and TLR2, demonstrating differences among PBT cell lines, which can be explained by various driving mutations and heterogeneity in glioma lines." (PMID 38449858, 2024). "Although RUNX2 and RUNX3 were also the malignant predictors of glioma, they have a poor specificity for distinguishing Mes types." (PMID 31754093, 2019).
bone cancer (14 papers, 2010 to 2025). A primary or metastatic malignant neoplasm affecting the bone or articular cartilage. "The promise of RUNX2 as a diagnostic and therapeutic target for bone cancer has grown as more has been learned about it." (PMID 37370857, 2023). "Notably, RUNX2 has been linked to both CSCs and bone cancer growth in prior research." (PMID 37370857, 2023). "In bone cancer, YBX1 stabilizes pro-metastatic mRNA by recognizing sequence motifs shared by the 3’ end of tRNA fragments(tRF)-GlyTCC and RUNX2, thereby inhibiting tumor metastasis in primary bone cancer progression." (PMID 40799245, 2025). "In primary bone cancer, RUNX2 is aberrantly overexpressed and physically interacts with YBX1, thereby exerting pro-metastatic effects." (PMID 38430423, 2024). "The functions of RUNX2 in the development and treatment of bone cancer were the primary foci of this review." (PMID 37370857, 2023). "Recent developments in the treatment of bone cancer, from RUNX2-based therapies to the establishment of drug resistance, were also addressed in depth." (PMID 37370857, 2023). "Our results support the emerging concept that the osteogenic transcription factor RUNX2 functions as a metastasis-related oncoprotein in non-osseous cancer cells." (PMID 21029421, 2010). "A number of recent studies have indicated that the osteogenic transcription factor RUNX2, is a suppressor of osteoblast growth, is frequently and aberrantly expressed in non-osseous cancer cells." (PMID 21029421, 2010). "Together, these findings point to a role for RUNX2 in BCSCs, in the diagnosis of bone cancer, and in treatment resistance, all of which provide credence to the hypothesis that RUNX2 might serve as a therapeutic target for anticancer drugs in the future." (PMID 37370857, 2023). "An analysis of 206 specimens of bone tumours showed that among the indicators with diagnostic utility, including SP7, IHH, RUNX2, SOX9 and TWIST1, only RUNX2, TWIST1 and SOX9 are sensitive and specific factors that differentiate between chondroblastoma and chondromyxoid fibroma." (PMID 29899399, 2018). "Thus, these RUNX2 target genes may contribute to the oncogenic activity of RUNX2 in osseous or non-osseous tumors." (PMID 21029421, 2010). "In conclusion, molecules such as RUNX2, CBX3, and MYC interact with YBX1 to promote tumor progression in various malignant tumors, including bone cancer, pancreatic cancer, and rhabdomyosarcoma, among others." (PMID 40799245, 2025). "Enhanced mechanical strength, excellent photothermal effect, osteogenesis of rBMSCs rabbit bone marrow stromal cells, increased expression levels of BMP2, RUNX2 and COL 1 osteogenic genes, inhibition of bone tumor and bone regeneration effects." (PMID 38791452, 2024). "A subpopulation of osteoblasts was identified in the bone tumor microenvironment in vivo of both humans and mice with bone metastatic breast cancer that express RUNX2/OCN/OPN but is negative for IL-6 and alpha-smooth muscle actin." (PMID 30813947, 2019).
chronic kidney disease (14 papers, 2016 to 2025). Impairment of the renal function secondary to chronic kidney damage persisting for three or more months. "In chronic kidney disease, Runx2 is deacetylated by SIRT6 to inhibit osteogenic trans differentiation of vascular smooth muscle cells." (PMID 39199205, 2024). "Up‐regulation of Runx2 is crucial for the calcification process, which was observed in vascular calcification of chronic kidney disease patients." (PMID 32845082, 2020). "Gemigliptin attenuated calcification of abdominal aorta and expression of RUNX2 in adenine-induced chronic kidney disease rats." (PMID 28686724, 2017). "This article primarily reviews the molecular mechanisms by which high phosphate, BMP2, and RUNX2 regulate vascular calcification secondary to chronic kidney disease, and discusses the complex interactions among these factors and their impact on the progression of vascular calcification." (PMID 39308809, 2024). "However, DKK1 can attenuate calcium deposition and the expression of RUNX2 in calcified aortas from chronic kidney disease in a similar manner to Cdon39." (PMID 36609601, 2023). "Furthermore, SIRT6 has been shown to protect the osteogenic transdifferentiation of vascular smooth muscle cells through RUNX2 in chronic kidney disease." (PMID 35249460, 2022). "The upregulation of the Runx2/Cbfa1 expression is crucial for the osteogenesis/ chondrogenesis phenotypic transformation and the start of the process of calcification, which was seen in the process of vascular calcification in patients with chronic kidney disease." (PMID 26907267, 2016).
osteonecrosis (13 papers, 2016 to 2026). A none disease characterized by death of bone tissue due to a lack of blood supply. "Disruption of osteoblastic differentiation can lead to osteonecrosis, demonstrated by the downregulation of osteoblast-specific markers such as RUNX2 and COL1A1 in the osteonecrosis of femoral head." (PMID 39407304, 2024). "In an experimental model of osteonecrosis of the femoral head, increased expression of Runx2 and osteocalcin was observed both four and eight weeks after EPO treatment." (PMID 37374263, 2023). "More recently, TNF-α was revealed to induce the inhibition of SATB2 and RUNX2 expression through microRNA-31 whereby inhibiting the osteogenic differentiation of BMSCs in ethanol-induced osteonecrosis." (PMID 35505281, 2022). "The involvement of NO pathway in SW osteogenic effect was previously reported in vitro, evidencing an increase in Bmp2 and RUNX2 transcription in marrow stromal cells of hips with osteonecrosis." (PMID 28158228, 2017). "In addition, TNF-α can reduce the expression of SATB2 and RUNX2 and promote osteogenic differentiation of BMSCs by decreasing microRNA-31 expression in ethanol-induced osteonecrosis." (PMID 35505281, 2022). "In this study, the expression levels of the osteogenic factor RUNX2 were downregulated in both GA-ONFH rats and DXMS-induced BMSCs, and YGY decoction was able to inhibit this decrease and improve osteonecrosis outcomes both in vivo and in vitro." (PMID 40319297, 2025). "Twenty-four rabbits were used to establish Osteonecrosis of the femoral head (ONFH) and randomly devided into four groups: Adenovirus Runx2 (Ad-Runx2) group, Runx2-siRNA group, MSCs group and Model group." (PMID 37029290, 2023). "Similar to miR-23a, miR-137-3p targets Runx2 and CXCL12, and its silencing can promote bone formation and angiogenesis, thus preventing osteonecrosis." (PMID 35909545, 2022).
ovarian carcinoma (13 papers, 2013 to 2024). A malignant neoplasm originating from the surface ovarian epithelium. "Our results were consistent with previous reports in thyroid and ovarian cancers in which miR-218 overexpression via lipid-based transfection downregulates Runx2 and inhibits cell proliferation, migration, and invasion in vitro." (PMID 37968694, 2023). "Results from independent studies, in ovarian cancer cell lines, also support the role of miR-23b-3p and miR-218-5p in RUNX2 regulation." (PMID 36362337, 2022). "Conversely, RUNX2 overexpression rescues ovarian cancer cells from the suppressive effect of miR-218-5p, inducing proliferation, colony formation, migration, and invasion." (PMID 36362337, 2022). "Together, these results suggest that RUNX2 is a critical transcription factor regulating SENP1 expression in platinum-resistant ovarian cancer." (PMID 33795649, 2021). "We still don’t know why and how RUNX2 levels are up-regulated in platinum-resistant ovarian cancer cells." (PMID 33795649, 2021). "Our study for the first time revealed that a transcription factor RUNX2 is responsible for the increased SENP1 mRNA level in cisplatin-resistant ovarian cancer cells." (PMID 33795649, 2021). "Thus, miR-23b-3p and miR-218-5p regulate the progression of ovarian cancer, in part, by repressing RUNX2." (PMID 36362337, 2022). "Our results suggest that the PTX treatment and acquiring of inverse resistance to PTX and CDDP may turn off (e.g., via negatively regulated RUNX2) the osteomimic phenotype in ovarian cancers cells, at least in vitro." (PMID 33287223, 2020). "Furthermore, the role of miR-338-3p in human ovarian epithelial carcinoma (EOC) was reported to inhibit ovarian cancer cell growth by targeting RUNX2." (PMID 27168985, 2016). "It suggests that ITGBL1 could remain under transcriptional control of RUNX2 also in ovarian cancer." (PMID 32961775, 2020). "Significantly, this novel SENP1/JAK2 axis is activated in platinum-resistant ovarian cancer in a manner dependent on a transcription factor RUNX2 and activated RUNX2/SENP1/JAK2 is critical for platinum-resistance in ovarian cancer." (PMID 33795649, 2021).
postmenopausal osteoporosis (13 papers, 2011 to 2023). Metabolic disorder associated with fractures of the femoral neck, vertebrae, and distal forearm. "Previously, we found that the miR338 cluster, a potential diagnostic and therapeutic target for postmenopausal osteoporosis, could directly target Runx2 during osteoblast differentiation in vitro." (PMID 36599929, 2023). "RUNX2 repression is strongly associated with postmenopausal osteoporosis and breast cancer." (PMID 32788656, 2020). "It is known that in age-related and postmenopausal osteoporosis, adipogenic differentiation of progenitor cells increases at the expense of osteogenic differentiation and our results showed that the different levels of Runx2 and PPARγ2 gene expression in MSCs-like may reflect this shift." (PMID 21674037, 2011). "Similarly, miR-214-5p overexpression diminished levels of ALP, Runx2, OCN and COLI, and TGFβ/Smad2 in bone marrow stem cells of postmenopausal osteoporosis." (PMID 33935961, 2020).
type 2 diabetes (13 papers, 2015 to 2025). "A considerable decrease was observed in the protein expression levels of Runx2, β-catenin, p-β-catenin, cyclin D1 and c-myc in BMSCs from type 2 diabetic rats compared with BMSCs from normal rats (p<0.05)." (PMID 26296196, 2015). "In addition, the activation of Runx2 promotes aortic valve fibrosis as well as aortic fibrosis and stiffness in patients with type 2 diabetes." (PMID 39199205, 2024).
acute myeloid leukemia (12 papers, 2015 to 2024). Acute myeloid leukemia (AML) is a group of neoplasms arising from precursor cells committed to the myeloid cell-line differentiation. "For example, inactivating RUNX1 mutations frequently occur in acute myeloid leukemia, where upregulation of RUNX2 or RUNX3 exhibits anti-leukemic effects." (PMID 30216339, 2018). "In addition, loss of RUNX1 increases RUNX2 mRNA level in acute myeloid leukemia cells, and depletion of RUNX2 increases RUNX1 mRNA expression in SaoS-2 and MDA-231 cells." (PMID 29050333, 2017). "The overexpression of RUNX2 has been reported in several tumors, including T-cell lymphoma, acute myeloid leukemia, and, recently, T-cell acute lymphoblastic leukemia (T-ALL)." (PMID 35886938, 2022). "The Runt-related transcription factor (RUNX) family, historically known as the polyoma enhancer-binding protein 2 α (PEBP2α), acute myeloid leukemia (AML) and core binding factor α (CBFα) family of proteins, comprises three members: RUNX1, RUNX2 and RUNX3." (PMID 36831308, 2023). "Genetic alterations of these genes (CBFB, RUNX1, RUNX2, and RUNX3) can alter normal binding to DNA by CBF, thus resulting in a failure of hematopoiesis or hematologic malignancies, particularly acute myeloid leukemia (AML)." (PMID 36011278, 2022).
bladder cancer (11 papers, 2017 to 2026). "There are limited studies in the literature addressing the role of RUNX2 in urinary bladder cancers." (PMID 42137676, 2026). "Our results showed that the expression levels of miR-154-5p and RSF1 were up-regulated in recurrent bladder cancer while RUNX2 was down-regulated, and the differences were insignificant." (PMID 36199571, 2022). "The fact that RUNX2 has been identified as an independent predictor of early tumor recurrence among BLCA patients suggests importance in terms of bladder cancer." (PMID 33718178, 2021). "Subsequent step-wise multivariate regression distilled the model to four independent predictors—NPM1 (HR = 1.42), RUNX2 (HR = 1.25), TET1 (HR = 1.41), and TIA1 (HR = 0.67)—thereby establishing a concise LLPS-related signature for risk stratification in bladder cancer." (PMID 41300366, 2025). "In addition, the overexpression of LINC01614 in bladder cancer could promote tumor proliferation, migration, and invasion through the miR-217/RUNX2 and Wnt/β-Catenin pathway." (PMID 36457749, 2022). "Furthermore, RUNX2 could predict early recurrence in bladder cancer patients with high accuracy." (PMID 35063012, 2022).
calcification (11 papers, 2017 to 2025). Process by which organic tissue becomes hardened by the physiologic deposit of calcium salts. "Nonetheless, genetic mutations like NOTCH1 mutations, lipoprotein metabolism genes, calcium signaling pathway genes, and runt-related transcription factor 2 (RUNX2) have been associated with valvular calcification." (PMID 40943088, 2025). "Coronary calcification was associated with 2.8-times-higher myeloid calcifying cell levels (p=0.037) and 50% elevated expression of the osteogenic gene RUNX2 in mononuclear cells, whereas expression of Sirtuin-7 (SIRT7) was inversely correlated with calcification." (PMID 35708762, 2022). "In this study, a new strategy of targeting the RUNX2 transcriptional machinery in CKD-induced vascular calcification is introduced." (PMID 38664060, 2024). "Integrative genomic study confirmed calcium signaling pathway genes RUNX2 and CACNA1C are associated with calcific disease." (PMID 35597927, 2022). "Runt-related transcription factor 2 (Runx2), an osteoblast-specific transcription factor, plays a crucial role in promoting osteogenic differentiation of VSMCs, which leads to medial arterial calcification (MAC) in MHD patients." (PMID 35080671, 2022). "In this study, we showed that RUNX2 expression is strongly increased by PDK4 activation and that the CML/RAGE/oxidative stress axis is important for the pathogenesis of diabetic vascular calcification." (PMID 29348870, 2017).